RNU6-261P (RNA, U6 small nuclear 261, pseudogene)
Gene: Small nuclear RNA gene on chromosome 6 (76,446,988 to 76,447,089, reverse strand). Ensembl gene ENSG00000238697.
Homologues: Orthologues: chimpanzee U6 (100% identical), macaque U6 (91% identical), mouse Gm24846 (75% identical), mouse Gm54952 (73% identical), pig U6 (73% identical), mouse Gm54497 (71% identical). Paralogues in human: RNU6-211P (83% identical), RNU6-1152P (81% identical), RNU6-1323P (81% identical), RNU6-196P (81% identical), RNU6-434P (81% identical), RNU6-1085P (80% identical), RNU6-1145P (80% identical), RNU6-116P (80% identical), RNU6-1316P (80% identical), RNU6-16P (80% identical), RNU6-20P (80% identical), RNU6-25P (80% identical), and 1286 more.